BRCA1 (BRCA1 DNA repair associated)
Diseases named in the same sentence as BRCA1 in open-access papers (continued):
Sharing a sentence is not in itself a finding about the gene and the disease.
cancer (continued). "The highest number of variants was found in the following genes: BRCA1 (52.9%; 45/85) with the most common variant p.Gln1756ProfsTer74 in 26.7% (12/45), BRCA2 (22.4%; 19/85) and other cancer associated genes constituting 24.7% (21/85) of variants." (PMID 36290365, 2022). "To resolve this, we employed methylation-specific droplet digital PCR (MS-ddPCR) to reassess the BRCA1 methylation status of the BRCA1meth cancer genomes in a quantitative manner." (PMID 35857626, 2022). "A deficiency in the HR pathway, such as BRCA1 and BRCA2 mutations, causes genomic instability and contributes to cancer development." (PMID 35563772, 2022). "This study utilized next-generation sequencing (NGS) to analyze the BRCA1/2 mutation profile, including LGR, in 56126 Chinese cancer patients." (PMID 36147908, 2022). "Following the initial discovery of synthetic lethality between PARP inhibition and BRCA1 or BRCA2 deficiency, other cancer types that harbor mutations in genes functioning in the DDR and DNA repair networks were also shown to be sensitive to PARP inhibition." (PMID 35022408, 2022). "Our results suggest that BRCA1 overexpression inhibits the Warburg effect, decreases cancer cell growth and migration, and enhances sensitivity to anti-cancer treatments via downregulation of PKM2 regulated by PI3K/AKT signaling." (PMID 36193432, 2022). "This is the largest series that prospectively measures cancer worry in BRCA1/2-PV carriers over time." (PMID 34997316, 2022). "The abrogation of MRE11 activity in BRCA1/2-deficient cells, on the other hand, was linked to PARP inhibitor resistance in cancer chemotherapy." (PMID 35501303, 2022). "Tumour testing of the BRCA1/2 genes is routinely performed in patients with different cancer histological subtypes." (PMID 35463374, 2022). "A high proportion of mutations were in BRCA1/2 genes, they were identified in 10% of OV cancer patients and 35.5% of BROV cancer patients." (PMID 35608067, 2022). "BRCA1 is involved to DNA repair, cell cycle regulation, transcription, ubiquitination, apoptotic activity, and sensitivity to anti-cancer drugs." (PMID 36193432, 2022). "Loss of function alterations in HRR-associated genes such BRCA1 and BRCA2, resulted in better response to poly ADP-ribose polymerase (PARP) inhibitor (PARPi) treatment in cancer patients." (PMID 35241075, 2022). "The Tier 2 pharmacogenes lacking a zebrafish ortholog included two members of the Cyp-family, Breast Cancer Type 1 (BRCA1), and the solute transporter SLC22A1." (PMID 36040978, 2022). "Females harboring germline BRCA1/BRCA2 (BRCA) P/LPV are offered a tight surveillance scheme from the age of 25–30 years, aimed at early detection of specific cancer types, in addition to risk-reducing strategies." (PMID 36230512, 2022). "Due to the well-established roles of BRCA1/2 in HR DSB repair, the PARPi hypersensitivity of BRCA1/2-deficient cancer cells was originally proposed to reflect their synthetic lethality." (PMID 36568963, 2022). "Patients had a mean age of 63.1 years, 8% (n = 151) were premenopausal, 17% (n = 337) had a known family history of BRCA1/2-related cancer, 88% (n = 1703) had HR+/HER2− disease, and 12% (n = 223) had TNBC." (PMID 36358816, 2022). "Leveraging the synthetic lethality between PARP inhibition and HRR deficiency, studies have established marked clinical benefit and a survival advantage from PARP inhibitors (PARPi) in mCRPC, most notably in cancers with BRCA1/2 alterations." (PMID 36497408, 2022). "More than two decades ago, the BRCA1 and BRCA2 susceptibility genes were discovered and cumulative risks of developing cancer were estimated." (PMID 35451682, 2022).
cancer (continued). "It has been reported that following exposure to the DNA cross-linking agent cisplatin, BRCA1 contributes to increased chemoresistance of cancer cells 36-38." (PMID 35541909, 2022). "BRCA1 and BRCA2 PV carriers are also known to have excessive risk to develop contralateral cancer 20 years after their initial cancer diagnosis." (PMID 35323371, 2022). "We have presented a large-scale BRCA1/2 screening in both cancer patients and cancer-free individuals throughout China." (PMID 35378767, 2022). "Intensive investigations into the mechanisms through which BRCA2 together with BRCA1 work as cancer suppressors have shown their key role as chromosome custodians with distinct functions which ensure the error-free resolution of DNA damage through HR repair." (PMID 35734584, 2022). "Frequency exceeding 1% was seen for several other cancer types (2 cancer types for BRCA1, 4 cancer types for BRCA2)." (PMID 35420638, 2022). "On the other hand, cancer cells belonging to C0, C1, and C4 had lower expression levels of HR-related genes, including BRCA1 and BRCA2." (PMID 35892844, 2022). "In cancers, reduced expression or loss of some NHEJ proteins including 53BP1 and Rev7 can lead to PARP inhibitor resistance in BRCA1-deficient cancers." (PMID 36362142, 2022). "Gains and losses are particularly characteristic for telomeric regions of BRCA1/2-related cancers, and this feature is defined as telomeric allelic imbalance." (PMID 36361916, 2022). "While BRCA1 and BRCA2 are the most well-studied genes, inclusion of other HCS genes will improve cancer risk prediction." (PMID 35877228, 2022). "Recent studies have shown the emerging role of reversions in BRCA1/2-mutant cancers, thereby conferring resistance to PARPi or platinum therapy." (PMID 36470901, 2022). "The results highlighted that BRCA1/2 and BRCAness genes shared high similarity of promoter hypermethylation across multiple cancer types." (PMID 36497135, 2022). "If this is a pathogenic variant in BRCA1 or BRCA2, the cells in the body harbouring the variant will have a predisposition to associated cancers." (PMID 36068545, 2022). "The variant rates of panel-gene (17.8% vs. 11.1%, p = 0.021) and BRCA1/2 (14.1% vs. 7.4%, p = 0.008) were higher in patients who presented a positive family history of any cancer." (PMID 36232564, 2022). "Thus, the BRCA1-deficient cancer cells may evolve some apoptotic resistance skills in vivo." (PMID 35517499, 2022). "Although the highly methylated cancers showed an average of more than an 8-fold decrease in BRCA1 gene expression compared to BRCA1 proficient cancers (P = 3.6E-8), patients with these methylated BRCA1 cancers did poorly with only 3/9 achieving pCR." (PMID 35857626, 2022). "Recent studies have demonstrated deep learning as a feasible and potentially useful tool for predicting germline BRCA1/2 status for cancer patients using demographic and clinical characteristics, medical images, or pathology images." (PMID 35209950, 2022). "Clinical testing for pathogenic variants in BRCA1 and BRCA2 has been established in clinical settings as it has been proven to improve cancer risk assessment and management of carriers." (PMID 35456503, 2022). "In the literature there are several studies of mutation in the BRCA1 and BRCA2 genes and association with different cancers." (PMID 35395863, 2022). "Our findings are consistent with other studies demonstrating racial/ ethnic and socioeconomic disparities in BRCA1/2 testing among individuals with cancer." (PMID 35312162, 2022). "This is the first study to reveal the BRCA1/2 LGR profile of a Chinese pan-cancer cohort by using an NGS-based assay." (PMID 36147908, 2022).
cancer (continued). "Carrier frequency for females and males in each cancer type was significantly correlated for BRCA1 and BRCA2 (eFigure 5 in the Supplement)." (PMID 35420638, 2022). "Our findings, based on actual expenditures from healthcare systems, indicate the advantage in expanding use of genetics for identification of women who are BRCA1/BRCA2 carriers, thus at high risk for developing cancer." (PMID 36551598, 2022). "We also provide an innovative therapeutic approach by targeting SSRP1 using CBL0137 to exert a synergistic anti-cancer activity with PARPi in BRCA1/2 wild-type and HR-proficient HGSC cells by impairing DNA repair via targeting HR pathway." (PMID 36539830, 2022). "Among these factors, mutations in tumor suppression genes breast cancer type 1 (BRCA1) and BRCA2 significantly increase the risk of OC, and these cancers can be prevented by chemoprevention and bilateral ovarian resection." (PMID 35335940, 2022). "Our data suggest that BRCA1 overexpression reverses the Warburg effect, inhibits cancer cell growth and migration, and enhances the sensitivity to anti-cancer treatment by decreasing PKM2 expression regulated by PI3K/AKT signaling." (PMID 36193432, 2022). "Based on the estimated overall risk for breast cancer protein-truncating variants, ATM, BRCA1, BRCA2, CHEK2 and PALB2 were identified as the major cancer susceptibility genes in the study population." (PMID 36568162, 2022). "Aberrant degradation of nascent DNA by MRE11 was observed in tumor suppressor BRCA1/2-deficient cells, and abrogation of MRE11 activity is linked to PARP inhibitor resistance in cancer chemotherapy." (PMID 35501303, 2022). "Some cancer drivers displayed both decreased accessibility and decreased mRNA levels, e.g., Brca1, E2f7 and Myh11, while others displayed increased accessibility and associated mRNA upregulation, e.g., Msi2, Bace2." (PMID 35269430, 2022). "We used data from 3,184 BRCA1 and 2,157 BRCA2 families in the Consortium of Investigators of Modifiers of BRCA1/2 to estimate age-specific relative (RR) and absolute risks for 22 first primary cancer types adjusting for family ascertainment." (PMID 35077220, 2022). "In this case-control study, we found normal tissue (WBC) BRCA1 promoter methylation to be associated with an elevated HR for incident TNBC and HGSOC (also when restricting analysis to cancers developing more than 5 years after WBC sampling)." (PMID 36074460, 2022). "Across these cancer types, the model achieved a PPV of 25%, indicating that only a fraction of the patients predicted HRD+ exhibited BRCA1/2-deficiency." (PMID 35643464, 2022). "BRCA1 mutant cancers show minimal resection of DSBs, which renders them deficient in homology-directed repair and sensitive to inhibitors of PARP1." (PMID 35785170, 2022). "Using NGS-based multi-gene panel testing, many cases with strong personal and/or family history of cancer were indeed found to be BRCA1/2-wild-type." (PMID 35858847, 2022). "In vitro, the exposure of BRCA1 and BRCA2 mutated cancer cells to cisplatin or PARPis favors the development of secondary genetic changes on the mutated allele which restore a functional protein and confer platinum and PARPis resistance." (PMID 35326571, 2022). "Under basal conditions, BRCA1-KO clones showed a significantly higher level of mean γH2AX signal intensity as well as a higher percentage of γH2AX positive cancer cells." (PMID 35619904, 2022). "When AML is addressed with DNA-damaging drugs or radiation therapy, BRCA1 activity is lost, leading to the accumulation of genomic abnormalities and cancer cell death." (PMID 35327610, 2022).
cancer (continued). "Mutations in PARP1 that prevent PARP1 trapping cause profound PARPi resistance in pre‐clinical in vitro and in vivo models of BRCA1 mutant cancer and have been seen in a single case of clinical PARPi resistance." (PMID 35567571, 2022). "Though BRCA1 and BRCA2 are associated with cancer risk, tumors that are identified as having “BRCAness” appear to be susceptible to specific therapeutic approaches." (PMID 35626055, 2022). "The results of this large-scale registry-based case-control study suggest that pathogenic variants in BRCA1 and BRCA2 were associated with the risk of 7 cancer types." (PMID 35420638, 2022). "The benefit of targeting homologous recombination pathway alterations has been limited to a few cancers with specific molecular signatures due to dysfunction of the HR pathway (BRCA1/2, ATM and HRD state)." (PMID 36358724, 2022). "Subsequent research revealed that many non-hereditary (sporadic) tumors share biological characteristics with BRCA1/2-driven cancers." (PMID 36361916, 2022). "Although there are indeed heritable mutations/genetic alterations that predispose to cancer and are therefore found in every cell that contains DNA (e.g., germline mutations in genes such as BRCA1 and BRCA2), these represent a minority of all cancer cases." (PMID 35703177, 2022). "For example, pioneering studies of SL partners in BRCA1 and BRCA2- deficient cancer cells identified PARP1." (PMID 35055413, 2022). "Our work resolves this conundrum by showing that BRCA1 methylation is a functionally plastic state within the cancer cell and that it can be rapidly lost upon chemotherapy exposure." (PMID 35857626, 2022). "The association of BRCA1 normal tissue methylation with higher risk for TNBC and HGSOC, the 2 major cancers associated with germline BRCA1 pathogenic variants, supports this conclusion." (PMID 36074460, 2022). "In past research, information has been noted by BRCA1/2 alteration carriers as a tool that can alter the potential course of cancer development." (PMID 35933387, 2022). "Patients had a mean age of 64.2 years, 6% (n = 26) were premenopausal, 15% (n = 63) had a known family history of BRCA1/2-related cancer, 80% (n = 325) had HR + /HER2− disease, and 20% (n = 82) had TNBC." (PMID 36358816, 2022). "To further demonstrate the role of ATF6 in protecting stressed cancer cells from cell death, preventing DNA damage, and sustaining the expression of BRCA-1, we silenced ATF6 prior exposing cells to DPE or Thapsigargin." (PMID 35752616, 2022). "Next, we aimed to identify candidate neoantigens to be used as a preventive cancer vaccine for germline BRCA1 carriers." (PMID 36298462, 2022). "High impact genes such as RB1 and BRCA1 are epigenetically inactivated at high frequencies which is why they were detected in the early days of molecular cancer research." (PMID 36084090, 2022). "Abolishing this gap filling role with an inhibitor that disrupts the interaction between REV1 and MAD2L2/REV3L is toxic to these HR-deficient cancer cells, including to PARP inhibitor-resistant BRCA1 mutant cells." (PMID 36075897, 2022). "Olaparib is the first FDA approved PARP small molecule inhibitor for BRCA1- and BRCA2-mutated cancers." (PMID 35328658, 2022). "The results of this case-control suggest that constitutional normal tissue BRCA1 promoter methylation is significantly associated with risk of incident TNBC and HGSOC, with potential implications for prediction of these cancers." (PMID 36074460, 2022). "BRCA1 is overexpressed in many type of cancers, including HCC, where its expression correlates with immune cell infiltration." (PMID 36557005, 2022). "In our full cohort, patients were at greater risk of carrying PV/LPV when risk prediction estimates were greater than 10.0% (for BRCA1) or when presenting three or more relatives with cancer (for BRCA1 and BRCA2)." (PMID 36329109, 2022). "Similar results were obtained when comparing BRCA1/2 mutant with BRCA1/2 wildtype cancers (p = 5.4E−4)." (PMID 36344511, 2022).
cancer (continued). "Persistently, high levels of cancer worry (≥ 14 at all three time points) were found in 106 (22%) BRCA1/2-PV carriers (55 BRCA1, 51 BRCA2)." (PMID 34997316, 2022). "Failure to resolve DSBs owing to loss-of-function mutations in genes encoding key players in the DNA damage response (DDR) — such as BRCA1, BRCA2 — and HR deficiency (HRD) has paved the way toward DDR-directed therapeutic strategies in several cancers." (PMID 35511434, 2022). "BRCA1-type cancers typically display small (<10 kb) tandem duplications, in contrast to BRCA2-type cancers." (PMID 35159019, 2022). "Patients had a mean age of 56.7 years, 27% (n = 52) were premenopausal, 68% (n = 131) had a known family history of BRCA1/2-related cancer, 73% (n = 141) had HR+/HER2− disease, and 27% (n = 53) had TNBC." (PMID 36358816, 2022). "In recent years, BRCA1/2 has attracted considerable attention as a biomarker for predicting cancer prognosis." (PMID 35409110, 2022). "FoundationOne® CDx, on the other hand, includes the percentage of genomic LOH (%LOH > 16) and next-generation sequencing of 315 genes, including HR-related genes extending beyond BRCA1/2, and other cancer-related genes such as NOTCH and MTOR." (PMID 36077694, 2022). "For instance, shared clonal mutations in driver genes such as ATM, ATRX, BRCA1/2, DAXX, MSH3, and MSH6 are associated with aberrations in major cellular signaling pathways like Pathways in cancer, DNA damage response, and regulation of cell cycle." (PMID 36140756, 2022). "We employed MS-ddPCR and reassessed the BRCA1 methylation status of the cancer genomes in the UW OvCa cohort in a quantitative manner." (PMID 35857626, 2022). "BRCA1 and BRCA2 are good examples of genes whose loss promotes cancer development but also make the cancer cell vulnerable to DNA damage." (PMID 36189922, 2022). "In a mouse BRCA1-mutant cancer model, tumors that are sensitive to PARP inhibitor olaparib acquire resistance following prolonged exposure to the drug." (PMID 36613695, 2022). "SIK2 inhibitors enhance olaparib sensitivity and inhibit tumor cell growth in both BRCA1/2 mutant and wild-type cancer cells." (PMID 35642638, 2022). "Massachusetts has the fewest uninsured residents of any state, the highest ratio of primary care physicians to residents, and Massachusetts' Medicaid program has consistently covered BRCA1/2 testing in individuals with cancer as recommended by NCCN guidelines." (PMID 35312162, 2022). "eFigure 7 in the Supplement describes associations between the carrier status in BRCA1 and BRCA2 for cases with a diagnosis of the 7 associated cancers and reported family history of each of these cancer types." (PMID 35420638, 2022). "BRCA1/2 alteration carriers require clear information on their cancer risks and on the options available to reduce these." (PMID 35933387, 2022). "Cancer worry was evaluated as part of the multicentre, prospective TUBA-study (NCT02321228) in which BRCA1/2-PV carriers choose either novel risk-reducing salpingectomy with delayed oophorectomy or standard risk-reducing salpingo-oophorectomy." (PMID 34997316, 2022). "Since the discovery of the role of BRCA1 and BRCA2 in hereditary BC, successful germline analysis of BRCA1, BRCA2, and other BC susceptibility genes has provided the foundation for genetics’ utility in screening, cancer risk reduction, and treatment." (PMID 35804819, 2022). "Applying the approach to separate between BA and MA alterations developed in the Methods section, we found that the percentage of BA alterations of all BRCA1/2 alterations varied across cancer types." (PMID 35681079, 2022). "In this systematic review it was found that the effect direction of mutations in BRCA1 and BRCA2 genes varies by cancer type." (PMID 35444210, 2022). "Patients with BRCA1 deficient cancers are also candidates for treatment with Poly (ADP-ribose) polymerase (PARP)-inhibitors, thus BRCA1 variant interpretation status is extremely important for treatment decisions." (PMID 34981296, 2022).